RNU6-943P (RNA, U6 small nuclear 943, pseudogene)
Gene: Small nuclear RNA gene on chromosome 11 (7,889,182 to 7,889,279, reverse strand). Ensembl gene ENSG00000252769.
Homologues: Orthologues: chimpanzee U6 (100% identical), macaque U6 (91% identical), dog U6 (76% identical), mouse Gm26226 (66% identical). Paralogues in human: RNU6-1131P (79% identical), RNU6-354P (79% identical), RNU6-610P (79% identical), RNU6-1024P (78% identical), RNU6-106P (78% identical), RNU6-1181P (78% identical), RNU6-41P (78% identical), RNU6-727P (78% identical), RNU6-829P (78% identical), RNU6-1287P (77% identical), RNU6-15P (77% identical), RNU6-166P (77% identical), and 1283 more.